NR4A3 (nuclear receptor subfamily 4 group A member 3)
Diseases named in the same sentence as NR4A3 in open-access papers (continued):
Sharing a sentence is not in itself a finding about the gene and the disease.
myeloid leukemia (4 papers, 2020 to 2024). A clonal proliferation of myeloid cells and their precursors in the bone marrow, peripheral blood, and spleen. "Overall, our study provides new cellular and clinical data supporting the idea that downregulation of NR4A3 is functionally associated with impaired differentiation in myeloid leukemias." (PMID 36040481, 2022). "Together, our findings demonstrate a tight association between impaired differentiation status and NR4A3 downregulation in myeloid leukemias, providing a plausible mechanistic explanation of how myeloid leukemogenesis might occur upon concurrent downregulation of NR4A1 and NR4A3." (PMID 36040481, 2022). "Although, it is likely that lncNR4A3 is a fine tuner of expression for several targets, far beyond NR4A3, we present evidence of a tumor suppressor role of this transcript in myeloid leukemia through the regulation of NR4A3." (PMID 33330042, 2020). "The analysis revealed a close association between differentiation status and different subtypes of AML Then, we probed the effects of differentiation-inducing treatments on NR4A3 expression and NR4A3 knockdown on cell differentiation using two myeloid leukemia cell lines." (PMID 36040481, 2022). "We next took advantage of established protocols for chemical induction of differentiation in NB4 and K562 myeloid leukemia-derived cell lines to test whether the NR4A3 expression level would be upregulated upon differentiation." (PMID 36040481, 2022). "Literature reports that NR4A3 is a tumor suppressor gene in myeloid leukemia." (PMID 34925506, 2021). "NR4A3 is reportedly a tumor suppressor gene in the development of myeloid leukemia." (PMID 34925506, 2021). "Furthermore, this and our other findings suggest the possibility that NR4A3-upregulating therapies may be applicable to myeloid leukemias." (PMID 36040481, 2022). "Moreover, our data suggest that targeting NR4A3 upregulation might yield novel differentiation therapies, and such treatments could have potential to be clinically beneficial for myeloid leukemias." (PMID 36040481, 2022). "NR4A1 and NR4A3 also function as tumor suppressors of myeloid leukemia, and downregulation of NR4A1 and NR4A3 expression is a common feature of the leukemic blast." (PMID 38539632, 2024).
Obesity (4 papers, 2010 to 2024). Accumulation of substantial excess body fat. "Moreover, upregulation of three NRs such as NR4A1, NR4A2, and NR4A3 can be used for the potential biomarkers for obesity while downregulation of NR1D1 can be used as a potential biomarker for obesity with rheumatoid arthritis as a complication." (PMID 29065888, 2017).
Autoimmunity (3 papers, 2020 to 2025). The occurrence of an immune reaction against the organism's own cells or tissues. "While this may indicate the importance of NR4A1/NR4A3 in clonal deletion, the cause of autoimmunity in this model is unclear, especially since these HDAC7 mutants demonstrated a generalized suppressive impact on the negative selection transcriptional program and impaired generation of Tregs." (PMID 33597928, 2020). "However this is in slight contradiction with the fact that autoimmunity and reduced lifespan was observed in Nr4a1/Nr4a3 but not in Nr4a2/Nr4a3 double deficient mice." (PMID 33597928, 2020). "Molecules that specifically inhibit Nr4a1 and Nr4a2, but not Nr4a3, are also candidates for tumor Treg-specific inhibitors, as Foxp3CreNr4a-DcKO mice do not develop autoimmunity but the mice do develop augmented antitumor immunity." (PMID 35514961, 2022).
depression (3 papers, 2022 to 2025). "Therefore, Nr4a3 and its associated genes are potential targets for developing treatments that suppress visceral sensitivity and alleviate depression in IBS-D." (PMID 38630738, 2024). "Building on animal experiments, we propose that SYNC can alleviate depression by downregulating the expression of CRH-R1 and Nr4a3 in the hypothalamus." (PMID 38630738, 2024).
endothelial dysfunction (3 papers, 2023). In vascular diseases, endothelial dysfunction is a systemic pathological state of the endothelium (the inner lining of blood vessels) and can be broadly defined as an imbalance between vasodilating and vasoconstricting substances produced by (or acting on) the endothelium. "Mechanistic studies uncovered that SOX17 promoted transcription and release of miR‐224‐5p and miR‐361‐3p, thereby targeting NR4A3 and PCSK9 to improve endothelial dysfunction." (PMID 36919784, 2023). "The “anti‐endothelial dysfunction (anti‐ED)” list consists of 31 genes that significantly ameliorate the ED phenotypes, with JUNB, NR4A3, SALL4, CSF2 and HEY1 being the top hits." (PMID 38031960, 2023).
neuroblastoma (3 papers, 2014 to 2025). Neuroblastoma (NB) is the most common solid, extracranial childhood tumor. "Since NR4A3 upregulation associated with the hypermethylation and neuronal differentiation in mice, poor prognosis of neuroblastoma associated with NR4A3 low expression may be partly explained by dysregulation of its differentiation." (PMID 24626568, 2014). "Immunohistochemical NR4A3 expression was generally faint in neuroblastoma tissues compared with normal tissues." (PMID 24626568, 2014). "Additional 17 neuroblastoma samples and 1 adrenal sample were used to confirm aberrant methylation at NR4A3 exon 3 CpGi." (PMID 24626568, 2014). "This is the first report indicating that DNA methylation level of NR4A3 exon 3 CpGi is associated with NOR1 expression and aberrantly methylated in neuroblastomas." (PMID 24626568, 2014). "In 17 out of 20 neuroblastoma specimens, methylation levels at NR4A3 exon 3 CpGi were low, compared with the average methylation level in 4 adrenal samples." (PMID 24626568, 2014). "In the analysis of neuroblastoma specimens, NR4A3 exon 3 CpGi showed low methylation level in neuroblastoma compared with adrenal samples." (PMID 24626568, 2014). "Twenty neuroblastoma patients were divided into two groups depending on their methylation levels at the NR4A3 exon 3 regions." (PMID 24626568, 2014). "The CpGi located between NR4A3 promoter and intron 1 was not methylated at all in either neuroblastoma or adrenal samples." (PMID 24626568, 2014). "A quantitative analysis of DNA methylation revealed that hypomethylation of CpG islands on NR4A3 exon 3, but not on exon 1 was identified in three neuroblastomas compared with matched adrenal glands." (PMID 24626568, 2014).
osteoarthritis (3 papers, 2020 to 2022). A noninflammatory degenerative joint disease occurring chiefly in older persons, characterized by degeneration of the articular cartilage, hypertrophy of bone at the margins and changes in the synovial membrane. "Similar reports in osteoarthritis indicated that overexpressing Nr4a3 activated IL-1β-induced NF-κB, and that downregulating Nr4a3 significantly inhibited IL-1β-induced NF-κB." (PMID 35922863, 2022). "Nuclear receptor subfamily 4 group A member 3 (NR4A3) is a proinflammatory factor in osteoarthritis." (PMID 35747513, 2022). "In this study, high expression of NR4A3 in human osteoarthritis (OA) cartilage was firstly observed." (PMID 31701670, 2020). "It is reported that NR4A3 is highly expressed in osteoarthritis, which may be related to the decrease of methylation level." (PMID 35747513, 2022). "It is reported that NR4A3 is highly expressed in human osteoarthritis cartilage tissue." (PMID 35747513, 2022).
Alzheimer disease (2 papers, 2018 to 2024). A progressive, neurodegenerative disease characterized by loss of function and death of nerve cells in several areas of the brain leading to loss of cognitive function such as memory and language. "Numerous studies have associated all hub genes identified from downregulated DEGs with Alzheimer’s disease (AD) and other neurological conditions like dementia and Parkinson’s disease, e.g., NR4A3, which is involved in the regulation of the immune system or MEF2D, which has a neuroprotective role." (PMID 39766348, 2024).
asthma (2 papers, 2019 to 2022). "PDK4 (P-value < 0.001) and ZBTB16 (P-value < 0.01) were up-regulated in asthma group, while WNT5A (P-value < 0.05), NR4A3 (P-value < 0.001) and WIF1 (P-value < 0.05) were down-regulated." (PMID 36550577, 2022).
autoimmune disease (2 papers, 2023 to 2025). A disorder resulting from loss of function or tissue destruction of an organ or multiple organs, arising from humoral or cellular immune responses of the individual to their own tissue constituents. "Loss of NR4A3 and other NR4A receptors in T cells blocks the development of Tregs, resulting in autoimmune diseases in multiple organs." (PMID 37532692, 2023). "Notably, Nr4a3-Tocky has been the most frequently used for the broadest range of applications including tumour immunology and immunotherapy NKT cell biology, and autoimmune disease." (PMID 39923022, 2025).
breast tumors (2 papers, 2016 to 2025). "Notably, NR4A3, a marker specific for salivary gland AciCC, is generally absent in breast cases, supporting the designation “carcinoma with acinar cell differentiation” for most breast tumors, although rare true salivary gland-type AciCCs with NR4A3 rearrangement have been documented." (PMID 41301002, 2025).
colorectal cancer (2 papers, 2023 to 2024). A primary or metastatic malignant neoplasm that affects the colon or rectum. "To address this, we utilised an autochthonous colitis-associated colorectal cancer model (CAC) in Nr4a3-Timer-of-cell-kinetics-and-activity-Ifng-YFP (‘Tocky-GreatSmart’) mice." (PMID 39558103, 2024). "Here, we used distal T cell receptor (TCR) and IFNγ reporter mice (Nr4a3-Tocky-Ifnγ-YFP) and a colorectal cancer (CRC) model to interrogate T cell activity during BCT with attenuated STm." (PMID 39558103, 2024).
follicular thyroid cancers (2 papers, 2020 to 2021). "Compared with thyroid follicular adenoma (FTA), NR4A3 was significantly down-regulated in follicular thyroid carcinoma (FTC), which led to reduced apoptosis factors." (PMID 34248843, 2021). "This contrasts to reports that NR4A3 acts as a tumor suppressor gene in lymphoreticular and follicular thyroid cancers." (PMID 32867110, 2020).
immune thrombocytopenic purpura (2 papers, 2022 to 2023). "miR-106b-5p induces immune imbalance of Treg/Th17 in immune thrombocytopenic purpura through NR4A3/Foxp3 pathway." (PMID 36980827, 2023). "have suggested that NR4A3 regulates Treg differentiation and maintains the Treg/Th17 balance to improve the symptoms of immune thrombocytopenic purpura." (PMID 35572523, 2022).
liver cancer (2 papers, 2024 to 2025). An epithelial or non-epithelial malignant neoplasm that arises from the liver. "Given the gender-specific disparity in liver cancer incidence as indicated by recent epidemiological data, it is plausible to hypothesize that the differential expression of NR4A3 between males and females may contribute significantly." (PMID 39664575, 2024). "Consequently, our subsequent investigation aims to elucidate whether the distinct NR4A3 expression in male liver cancer patients exerts an influence on their prognosis." (PMID 39664575, 2024).
mesenchymal neoplasm (2 papers, 2018 to 2021). "Recently, EMC has been reported to carry the translocation of the NR4A3 gene, but other myxoid mesenchymal neoplasms do not belong to the EWSR1‐NR4A3 category." (PMID 33713576, 2021).
pancreatic cancer (2 papers, 2014 to 2019). "Since TGFBR2 has been proved to be a target of miR-665 in pancreatic cancer and other cancer cells, we only focued on the novel target, NR4A3, of miR-665 in BC." (PMID 31209222, 2019).
prostate carcinoma (2 papers, 2016 to 2023). A carcinoma that arises from epithelial cells of the prostate gland. "In our previous research on prostate cancer, we found that NR4A3 is one of the downstream target genes of RP11-495P10.1." (PMID 37905340, 2023). "Interestingly, over-expression of NR4A3/NOR1 also inhibited prostate cancer cell growth and reduced the levels of anti-apoptotic proteins BCL2 and BCL-XL49." (PMID 27586588, 2016).
pulmonary arterial hypertension (2 papers, 2021 to 2025). Pulmonary arterial hypertension (PAH) is a group of diseases characterized by mean pulmonary artery pressure >20 mmHg and elevated pulmonary arterial resistance leading to right heart failure. "In patients with pulmonary arterial hypertension (PAH), the pulmonary artery smooth muscle cells (PASMCs) exhibited increased proliferation and survival and decreased expression of NR4A1, NR4A2, and NR4A3 (protein and mRNA) compared to normal lung PASMCs." (PMID 40871737, 2025).
salivary gland neoplasm (2 papers, 2019 to 2020). Tumors of the SALIVARY GLANDS. "Split signals indicating a NR4A3 gene locus rearrangement were present in 24 of 28 evaluable AciCCs (86%), while no NR4A3 translocation was observed in any of 75 non-AciCC salivary gland tumors." (PMID 30664630, 2019). "However, unlike fusion transcripts that occur in other salivary gland tumors, which result in the production of fusion proteins like the MYB-NFIB fusion genes produced in adenoid cystic carcinoma, in this case the result is a more highly transcribed NR4A3 or NR4A2 gene, but no fusion proteins." (PMID 32867110, 2020).
Sepsis (2 papers, 2022 to 2024). Sepsis is defined as life-threatening organ dysfunction caused by a dysregulated host response to infection. "PDPNA binds NR4A1, NR4A2, and NR4A3 but inhibits sepsis only through NR4A1." (PMID 38540704, 2024). "Hence, we speculated that circ_UBE2D2 may influence the process of renal injury in sepsis by targeting miR-370-3p to promote NR4A3 expression." (PMID 35722711, 2022).
synovial sarcoma (2 papers, 2022 to 2025). "In this study, histology‐specific fusion genes were identified in nine cases, including SYT::SSX1 in synovial sarcoma, EWSR1::FLI1 in ES, and EWSR1::NR4A3 in EMC." (PMID 40755265, 2025).
Arthritis (1 paper, 2024). Inflammation of a joint. "The genes with the most significantly increased expression in the synovial tissues of the arthritis-protected Mg2800 diet group included Actc1 (actin alpha cardiac muscle 1) and Nr4a3 (nuclear receptor subfamily 4 group A member 3)." (PMID 39683640, 2024). "The genes with the most significantly increased expression in the synovial tissues of the arthritis-protected Mg2800 diet group included Snora34, Gnrh1, Actc1, Nr4a3, and Slc9a4." (PMID 39683640, 2024).
atopic dermatitis (1 paper, 2022). "This is also true of studies probing NR4A3 expression in eosinophils of patients with atopic dermatitis." (PMID 36040481, 2022).
basal cell carcinoma (1 paper, 2024). A carcinoma involving the basal cells. "Microarray analysis also revealed an upregulation in ALDH1A3 and NR4A3, which are genes that have since been identified as being commonly recognized biomarkers for carcinoma-associated fibroblasts (CAFs) in skin disorders including basal cell carcinoma and systemic sclerosis." (PMID 38948860, 2024).
bipolar disorder (1 paper, 2022). A disorder of the brain that causes unusual shifts in mood, energy, activity levels and the ability to carry out day-to-day tasks. "They showed that the NR4A3 marker rs1131339 is significantly associated with the risk of smoking and the degree of smoking in a population of individuals with bipolar disorder." (PMID 35893041, 2022).
brain tumors (1 paper, 2019). "The present study demonstrates that NR4A3 inhibition significantly inhibited HBMEC angiogenic transformation and may be used to target brain tumors." (PMID 31920707, 2019).
breast disease (1 paper, 2024). "A dysregulated NR4A3 may exacerbate these conditions by upregulating ENO3, increasing glycolytic activity, and contributing to disorders like wooden breast disease." (PMID 39765464, 2024).
cervical cancer (1 paper, 2025). A primary or metastatic malignant neoplasm involving the cervix. "However, several DMRs near the NR4A3 promoter were unmethylated on the integrated allele, including an 821 bp DMR in exon two of NR4A3 at the 3′ end of an unmethylated promoter element (bottom), distinguishing it from other cervical cancer samples we profiled (bottom)." (PMID 39638560, 2025).
cervicitis (1 paper, 2024). An acute or chronic inflammatory process that affects the cervix. "NR4A3 was significantly expressed in CIN I (p < 0.05) and NR4A2 was expressed in both cervicitis and CIN III (p > 0.05)." (PMID 39639963, 2024). "Regarding the orphan receptor NR4A3, a significant increase in its expression was found in patients with CIN I when compared with cervicitis and CIN III (p = 0.0366)." (PMID 39639963, 2024).
cocaine addiction (1 paper, 2017). "Our results further demonstrated that Nr4a1 persistently increased while Nr4a2 and Nr4a3 showed transient changes after cocaine withdrawal, indicating their different roles in different stages of cocaine addiction." (PMID 28386228, 2017).
cognitive disorder (1 paper, 2023). A disease affects cognitive processes. "Among these genes were key transcriptional regulators (e.g., Ahr, Id2, Nr4a1, Nr4a3, Olig2, Zbed4), sustaining previous evidence that several severe cognitive disorders are associated with alterations in transcriptional regulatory activity." (PMID 37048129, 2023).
colitis (1 paper, 2024). Inflammation of the colon. "In this study, we combined an autochthonous colitis-associated CRC mouse model using STmΔaroA (an attenuated aromatic amino acid auxotrophic mutant) with the Nr4a3-Tocky-Ifng-YFP kinetic TCR-cytokine reporter, which has recently been utilised to detect favourable responses to ICB." (PMID 39558103, 2024).
colon cancer (1 paper, 2020). "Notably, upon analysis of bulk RNA in the 32 colon cancer patient samples, we found that ciRS-7 was significantly positively correlated with FOS (r = 0.84, P < 0.0001), NR4A3 (r = 0.80, P < 0.0001) and PIK3CD (r = 0.40, P = 0.02)." (PMID 32917870, 2020).
gastric tumor (1 paper, 2016). "To investigate the clinical significance of NR4A3 methylation in gastric carcinogenesis, we performed quantitative methylation-specific PCR (qMSP) to analyze NR4A3 methylation in human gastritis and primary gastric tumor samples." (PMID 27528092, 2016).
glioblastoma (1 paper, 2024). The most malignant astrocytic tumor (WHO grade IV). "NR4a3 has anti-oxidative activity in glioblastoma cells and has been suggested to have tumor-suppressive activity." (PMID 39683640, 2024).
insomnia (1 paper, 2024). A sleep disorder characterized by difficulty in falling asleep and/or remaining asleep. "Likewise, NR4A3 was significantly (P < 0.05) associated with metabolic (e.g., fat-free mass), nervous/neurological (e.g., neuroticism and insomnia) and cardiovascular (e.g., resting heart rate) traits and was dynamically expressed in adipose, cerebellum, heart and artery." (PMID 38730227, 2024).
intervertebral disc degeneration (1 paper, 2024). "This study aimed to reveal the specific role of early growth response protein 1 (EGR1) and nuclear receptor 4A3 (NR4A3) in nucleus pulposus cells (NPCs) and the related molecular mechanism and to identify a new strategy for treating intervertebral disc degeneration (IVDD)." (PMID 38943627, 2024).
ischemia (1 paper, 2015). A hypoperfusion of the BLOOD through an organ or tissue caused by a PATHOLOGIC CONSTRICTION or obstruction of its BLOOD VESSELS, or an absence of BLOOD CIRCULATION. "One of the genes most upregulated by α1aAR stimulation was Nr4a3, a medically important member of a family of transcription factors frequently activated by cellular stress including ischemia." (PMID 26244980, 2015).
Lewy body disease (1 paper, 2020). "Nuclear receptor subfamily 4 group A member 3 has been involved in Lewy body disease and multiple system atrophy." (PMID 32736565, 2020).
lung adenocarcinoma (1 paper, 2023). A carcinoma that arises from the lung and is characterized by the presence of malignant glandular epithelial cells. "Furthermore, lncRNA BRE-AS1, through the upregulation of NR4A3, elicits inhibitory effects on the growth and survival of lung adenocarcinoma cells." (PMID 37965447, 2023).